RAD52 (RAD52 DNA repair protein)
Diseases named in the same sentence as RAD52 in open-access papers (continued):
Sharing a sentence is not in itself a finding about the gene and the disease.
cancer (continued). "Recent studies in ALT cancer cells found that telomere recombination can proceed through multiple mechanisms, including POLD3-dependent break-induced telomere synthesis and RAD52-dependent mitotic telomeric DNA synthesis." (PMID 32620872, 2020). "Overall, this concept highlights Rad52 as a potential therapeutic target in tumors with inactive BRCA2 and helps explain why Rad52 gene amplifications are selected for in human cancers." (PMID 29548335, 2018). "Therefore, we hypothesize that RAD52 may be involved in platinum resistance in cancer cells." (PMID 23209746, 2012). "Blocking RAD52 activity in cancer cells lacking BRCA1/2 proves fatal, underscoring the critical importance of RAD52 in the DNA repair process." (PMID 38136334, 2023). "RAD52 is not an essential gene in normal cells, and thus RAD52 is an optimal drug target for cancer treatment." (PMID 36470428, 2022). "In summary, RAD52 and SSA may belong to the main sources of genomic instability, vital for cancer induction and development, so they can be considered in anticancer strategies." (PMID 33671579, 2021). "Cells lacking both RAD52 and SLX4 are synthetically lethal due to the accumulation of genomic abnormalities, and thus are potential therapeutic targets in cancers that are telomerase deficient." (PMID 34887904, 2021). "RAD52, the essential SSA protein, is an important target in cancer therapy." (PMID 33671579, 2021). "Importantly, the HR gene RAD52 has been found to be synthetically lethal to the tumor suppressor gene BRCA2; this represents an important finding to design more precise cancer therapies." (PMID 32656256, 2020). "Moreover, several other compounds targeting proteins involved in DNA repair mechanisms have already shown promising results as potential new anti-cancer drugs in pre-clinical studies, such as BLM, WRN, RAD52, or MRE11 inhibitors." (PMID 33036275, 2020). "Since CHK1 inhibitors are being tested in clinical trials, combining RAD52 and CHK1 inhibition might prove a much more effective strategy to kill cancer cells, especially cancer stem cells." (PMID 32050645, 2020). "Since cancer cells are often characterized by ALT phenotype, overexpression of RAD52 might correlate with capability to proliferate in uncontrolled manner." (PMID 32050645, 2020). "DNA repair pathways, such as those involving RAD52 and INO80, are evolutionarily conserved, involved in genome instability and tumorigenesis, and predictive of therapeutic response in some cancers, thus representing potential tumor-specific biomarkers for chemotherapeutic efficacy." (PMID 31660150, 2019). "Both features of DNA re-replication-induced replication stress and deficient TLS lead to enhanced formation of the highly deleterious DSBs that are repaired in an error-prone manner, by Rad52-dependent BIR and SSA, thereby fueling genomic instability and promoting cancer development." (PMID 29548335, 2018). "Conversely, we demonstrated that only the CROCC-associated signature, which included the DNA homologous recombination factor RAD52, the tumour suppressor gene HIC1 and the repressor of the sonic hedgehog pathway TULP3, had a prognostic value in ER-negative/HER2-negative cancers." (PMID 29559730, 2018). "We therefore tested whether combined inhibition of APE1 and Rad52 sensitizes cancer cells lacking INO80 or RNase H1 to death." (PMID 32913330, 2020). "Furthermore, we show that Rad52 was upregulated transcriptionally in a manner dependent on E2F1, a transcription factor that also drives G1/S transition and which is frequently overexpressed in cancer." (PMID 29548335, 2018). "Inhibiting tumor-specific DSB repair pathways, such as those involving RAD52, may function by amplifying DNA damage, overloading the cancer cell with genomic instability to the point where it can no longer thrive." (PMID 28722656, 2017). "Thus, developing therapeutic strategies targeting RAD52 to treat PALB2, BRCA1 or BRCA2 mutant cancers might be considered." (PMID 26610585, 2015).
cancer (continued). "Thus, combining PARP1 and RAD52 inhibitors to treat BRCA1 or BRCA2 mutant cancers might provide little or no therapeutic gain, and might increase normal tissue toxicity." (PMID 29145865, 2017). "Since the concept of synthetic lethality relies on the addiction of cancer cells to a single DNA repair pathway, whereas normal cells operate their DNA damage response by way of two or more mechanisms, non-cancerous cells did not have to rely on Rad52 for constant repair and were left unharmed." (PMID 28722656, 2017). "Further, our identified role for PolQ in mitosis is relevant to human cancer, as cancer cells lacking the BRCA2 or RAD52 repair proteins rely heavily on PolQ-mediated alt-EJ repair in mitosis." (PMID 34946831, 2021). "No gene is found down-regulated in all three cancer subtypes at once: SP100 loses expression in LS-CRC and MSS s-CRC, while RAD52 deactivates in MSS and MSI s-CRC." (PMID 31750255, 2019). "Without HR and the RAD52-dependent backup pathway, the BRCA1 mutant cancer cells depleted of EEPD1 skew to the alternative non-homologous end-joining DNA repair pathway for survival." (PMID 29145865, 2017). "This suggests that inhibition of F2 (for example RAD54/RAD54B) would be particularly effective to sensitize cancer cells overexpressing F1 components (e.g. RAD51 paralogs, RAD51, RAD52, BRAC2), a non-intuitive insight derived from the mathematical modeling." (PMID 23592964, 2013). "Moreover, the BTR complex localizes to telomeres and, together with FANCM and RAD52, is involved in alternative lengthening of telomeres (ALT), a recombination-dependent telomere maintenance pathway used by telomerase-negative cancers to achieve replicative immortality." (PMID 36894693, 2023).
tumor (57 papers, 1999 to 2025). "RAD52-mediated DNA repair remains active in PARPi-treated BRCA-deficient tumor cells such that dual inhibition of RAD52 and PARP1 have demonstrated evidence of synthetic lethality in a BRCA-deficient mouse model." (PMID 35626165, 2022). "When RAD52 is knocked out in BRCA1- or BRCA2-deficient tumor cells, HRR frequency is significantly reduced." (PMID 34484285, 2021). "Several studies reported an association between high RAD52 expression level in tumor samples with poor patient prognosis and disease prognosis." (PMID 34887904, 2021). "A high score for RAD52 expression in the tumour centre was significantly associated with worse disease-free survival (DFS; p = 0.045)." (PMID 32143539, 2020). "This RAD52 mutation causes a reduction in DSB repair by SSA, suggesting that defects in RAD52‐dependent DSB repair are linked to reduced tumor risk in BRCA2‐mutation carriers." (PMID 32175645, 2020). "RAD52 expression levels in the tumour centre (TC) were significantly associated with lymph node (LN) involvement (p = 0.028)." (PMID 32143539, 2020). "Our model of RAD52/POLθ pathway increase at stalled replication forks promoting secondary mutation driving resistance is further supported by our understanding of tumor resistance biology." (PMID 29334356, 2018). "Loss of Rad52 increases genomic instability beyond a manageable threshold and consents the damaged cells to death before they are able to become tumor cells." (PMID 28722656, 2017). "In order for these HR-deficient tumor cells to proliferate, they become addicted to a bypass replication fork repair pathway mediated by radiation repair protein 52 (RAD52)." (PMID 29145865, 2017). "Loss of Rad52, however, appears to increase genomic instability beyond a manageable threshold, acceding the damaged cells to death before they are able to become tumor cells." (PMID 28415565, 2017). "Loss of Rad52 appears to increase genomic instability beyond a manageable threshold, consenting the damaged cells to death before they are able to become tumor cells." (PMID 28415565, 2017). "Researchers in the Skorski group have identified compounds capable of disrupting ssDNA binding by RAD52 and which consequently exerted anti-tumor activity against BRCA-mutated carcinoma cells." (PMID 28722656, 2017). "It has been reported that inhibition of RAD52 either by specific shRNA or a small peptide aptamer induced synthetic lethality in tumor cell lines carrying BRCA1 and BRCA2 inactivating mutations." (PMID 26784987, 2016). "As Rad52 is required for cellular proliferation in BRCA2-defective cells, silencing of Rad52 could cause BRCA2-defective tumour cells." (PMID 36010882, 2022). "Interestingly, we found that RAD52 expression levels in the tumour periphery (TP) were associated with age group; patients older than 71 years exhibited significantly higher RAD52 expression than other age groups (p = 0.018)." (PMID 32143539, 2020). "These two opposing roles of RAD52-dependent SSA make it a potential target of chemotherapy to treat RAD51-deficient tumour, as RAD52 inactivation may specifically inhibit the tumour growth and block additional rearrangements of chromosomes." (PMID 32355220, 2020). "To test whether depletion of Rad52 inhibits FANCM-deficient tumor growth, we monitored tumor formation in a mouse xenograft model." (PMID 30022024, 2018). "In syngeneic mice, ID8-OR cells in which Rad52 was knocked out yielded lower tumor burden and longer overall survival than control cells." (PMID 41040355, 2025). "F79 was designed to inhibit RAD52 and exert synthetic lethality in BRCA-disrupted and/or HR-mutated tumor cells." (PMID 36980703, 2023). "Deletion of Rad52 increased tumor cell death and reduced growth compared to wild-type (WT) mice that appeared to be due to enhanced Rad52-/- NK and CD8+ T-cell effector functions." (PMID 37817767, 2023).
tumor (continued). "Currently, inhibiting RAD52 and/or PARP1 in the tumor cells that are deficient in the canonical repair pathways has been the potential target for inducing the effect of synthetic lethality." (PMID 35741863, 2022). "Inactivation of Rad52 in BRCA2-deficient cells results in synthetic lethality, which makes Rad52 a tumour-specific target for therapy in BRCA2-deficient tumours." (PMID 36010882, 2022). "To determine the in vivo effect of curcumin on RAD52 expression, we subjected tumor sections to immunohistochemistry (IHC)." (PMID 33922657, 2021). "RAD52 is a crucial human deoxyribonucleic acid (DNA) repair gene involved in maintaining genomic stability and preventing tumor occurrence." (PMID 34106670, 2021). "The correlation between RAD52 overexpression and accelerated hepatocarcinogenesis in TGF-α/c-myc transgenic mice was the first significant evidence that highlighted the importance of RAD52 in tumor development." (PMID 34887904, 2021). "In contrast, reduced RAD52 expression in tumour centre samples from patients treated with neoadjuvant therapy (n = 40) significantly correlated with poor DFS (p = 0.025) and overall survival (OS; p = 0.048)." (PMID 32143539, 2020). "RAD52 is a DNA-binding protein involved in the homologous recombination in DNA repair, and is important for the maintenance of tumour genome integrity." (PMID 32143539, 2020). "Exploitation of the synthetic lethal relationship between defects in BRCA1 and BRCA2 tumour suppressors and with RAD52 depletion or inhibition has opened many new questions into the role of the RAD52 protein in genome maintenance." (PMID 31799622, 2020). "We also assessed correlations between RAD52 expression and tumour response to neoadjuvant radiotherapy, combined with 5-FU treatment." (PMID 32143539, 2020). "It appears that RAD52 plays a key role in the maintenance of tumour genome integrity and furthermore is involved in the response to oncogene-induced DNA replication stress." (PMID 32143539, 2020). "RAD52 expression in 413 tissue samples (50 normal tissues and 363 tumor tissues) at the mRNA level was obtained from the TCGA database in this research." (PMID 31719794, 2019). "High expression of RAD52 was detected in tumor cells, particularly in the lung squamous cell carcinomas and nasopharyngeal carcinoma tissues in previous studies." (PMID 31719794, 2019). "Conversely, depletion of RAD52 not only decreased the rate of tumor cell growth but also increased DNA damage and subsequently halted tumor cells at the G2 phase of the cell cycle." (PMID 28722656, 2017). "We determined that loss of Rad52 in murine CD8+ T cells and NK cells increases tumor cell cytotoxicity as measured by cell-associated luciferase activity." (PMID 28415565, 2017). "Although RAD52 functions in a similar manner to the BRCA2 tumor suppressor, repairing DNA damage in order to stabilize cell homeostasis and viability, expression of RAD52 has recently been linked to several different forms of tumorigenesis." (PMID 28722656, 2017). "Ex vivo analysis of these cell populations revealed that Rad52 knockout CTLs, as well as NK cells, have enhanced anti-tumor activity compared to wild type." (PMID 28415565, 2017). "It has been reported that miR-302a involves in maintaining stemness of hESCs, suppressing tumor cell proliferation and inducing cancer cell apoptosis by directly targets Rad52 and AKT1." (PMID 29088754, 2017). "New evidence suggests that RAD52, a component of the homologous recombination pathway, is important for the maintenance of tumor genome integrity." (PMID 28722656, 2017). "In this report, we analyze the phenotypic differences between wild type and Rad52−/− in inhibition of tumor phenotypes including cell growth, viability, cytolysis, and immune profiling." (PMID 28415565, 2017). "Our recent work suggests that cell death, tumor inhibition, and immunity are enhanced in mouse cells depleted of RAD52." (PMID 28722656, 2017).
tumor (continued). "Our results provide evidence that miR-302a synergistically increases the sensitivity of AML cells to VP-16 and demonstrate that miR-302a downregulates Rad52 to inhibit tumor growth and chemoresistance, in part via the AKT/Gsk-3β/β-catenin signaling cascade." (PMID 29088754, 2017). "In this report, we dissect the phenotypic distinctions between wild type and Rad52−/− in inhibition of tumor phenotypes including cell growth, viability, cytolysis, and immune profiling." (PMID 28415565, 2017). "Recently, it was reported that PTEN, an important tumor suppressor, physically interacts with RAD52 in response to DNA damage and is involved in regulation of RAD52 sumolyation in the nucleus." (PMID 27649245, 2016). "We additionally identified rs10849605 as a RAD52 cis-eQTL inUADT(p = 1x10−3) and LUSC (p = 9x10−4) tumours, with the UADT/LUSC risk allele correlated with increased RAD52 expression levels." (PMID 25793373, 2015). "The improvement in survival was associated with a marked in vivo depletion in ATR, CHK1 and RAD52, but induction of γ-H2AX, cleaved Caspase 3 and BIM in the engrafted tumor cells following 1 week of treatment with the combination." (PMID 25026298, 2014). "To identify novel tumor-specific promoters, we examined expression levels of Rad51 paralogs, Rad51B, Rad51C, and Rad51D as well as Rad52 in a panel of normal and tumor cell lines." (PMID 24742710, 2014). "LOH was found in the RAD51 region in 32% of tumours, in the RAD52 region in 16%, in RAD54 in 20% and in the BRCA1 and BRCA2 regions in 49% and 44% respectively." (PMID 10507777, 1999). "Tumor suppressor, regulates cell signaling pathways, impacts RAD52 function." (PMID 41409896, 2025). "When RAD52 is overexpressed in certain tumors, inhibition of RAD52 may enhance the therapeutic sensitivity of tumor cells." (PMID 39796194, 2025). "Rad52 also represents a potential therapeutic target because no Rad52 mutations or inactivation has been documented in tumours." (PMID 36010882, 2022). "Our results provide strong rationale for the use of HR inhibitors, as well as ATRi (which are also known to indirectly suppress HR) in particle therapy to further sensitize tumor cells and also suggest the use of RAD52 and PARP1 inhibitors to further enhance efficacy." (PMID 36263011, 2022). "Moreover, decreased expression of RAD52 partially counteracted the tumor-promoting effect of SF3B4 overexpression." (PMID 35210412, 2022). "Defects in homologous recombination pathway-related genes RAD54, RAD51 and RAD52 could lead to tumour development." (PMID 35689754, 2022). "However, further studies with larger patient numbers are certainly needed to estimate and characterize the association of RAD52 expression and MMR protein expression in tumours." (PMID 32143539, 2020). "Moreover, it has been shown recently, that simultaneous inhibition of PARP1 and RAD52 can have a synergistic effect on the tumor cell killing." (PMID 32050645, 2020). "New evidence suggests that RAD52 is essential for maintaining tumor genome integrity." (PMID 31719794, 2019). "Moreover, PTEN, an important tumor suppressor, seems to physically interact with RAD52 in response to DNA damage and is involved in the regulation of RAD52 sumolyation in the nucleus." (PMID 31652722, 2019). "RAD52 inhibitors may also be useful outside the realm of BRCA deficiency, as depletion of RAD52 was shown to decrease tumor volume in FANCM-deficient tumors in mice." (PMID 31340507, 2019). "Disrupting either the DNA annealing factor RAD52 or the A-family DNA polymerase POLQ can cause synthetic lethality with defects in BRCA1 and BRCA2, which are tumor suppressors important for homology-directed repair of DNA double-strand breaks (DSBs), and protection of stalled replication forks." (PMID 31381562, 2019). "Abnormal expression of RAD51 and RAD52 can contribute to genomic instability and tumor progression." (PMID 31719794, 2019).